RNU4-68P (RNA, U4 small nuclear 68, pseudogene)
Gene: Small nuclear RNA gene on chromosome 14 (103,567,405 to 103,567,545, forward strand). Ensembl gene ENSG00000201184.
Homologues: Orthologues: chimpanzee U4 (100% identical), macaque U4 (91% identical), rat LOC120098030 (57% identical). Paralogues in human: RNU4-7P (89% identical), RNU4-42P (88% identical), RNU4-58P (88% identical), RNU4-13P (86% identical), RNU4-67P (86% identical), RNU4-31P (85% identical), RNU4-45P (84% identical), RNU4-76P (84% identical), RNU4-92P (84% identical), RNU4-80P (84% identical), RNU4-8P (84% identical), RNU4-12P (83% identical), and 81 more.